PNPLA3 (patatin like domain 3, 1-acylglycerol-3-phosphate O-acyltransferase )
Description:
Specifically catalyzes coenzyme A (CoA)-dependent acylation of 1-acyl-sn-glycerol 3-phosphate (2-lysophosphatidic acid/LPA) to generate phosphatidic acid (PA), an important metabolic intermediate and precursor for both triglycerides and glycerophospholipids. Does not esterify other lysophospholipids. Acyl donors are long chain (at least C16) fatty acyl-CoAs: arachidonoyl-CoA, linoleoyl-CoA, oleoyl-CoA and at a lesser extent palmitoyl-CoA. Additionally possesses low triacylglycerol lipase and CoA-independent acylglycerol transacylase activities and thus may play a role in acyl-chain remodeling of triglycerides. In vitro may express hydrolytic activity against glycerolipids triacylglycerol, diacylglycerol and monoacylglycerol, with a strong preference for oleic acid as the acyl moiety. However, the triacylglycerol hydrolase activity is controversial and may be very low. Possesses phospholipase A2 activity.
Synonyms: ADPN; C22orf20; dJ796I17.1; FLJ22012; adiponutrin; iPLA2epsilon; iPLA(2)epsilon
Tractability: Antibody: UniProt predicts a signal peptide or a membrane-spanning region.
Safety:
Unwanted effects reported when the protein is acted on. In parentheses: how it was acted on, where the effect was seen, and who reports it.
alcoholism (source: ClinPGx)
hepatotoxicity (source: ClinPGx)
Gene: Protein-coding gene on chromosome 22 (43,923,781 to 43,964,488, forward strand). Ensembl gene ENSG00000100344.
Subcellular location: Membrane; Lipid droplet
Subcellular location (Human Protein Atlas): Nucleoli; Cytosol; Mitochondria
Pathways (Reactome):
Metabolism: Acyl chain remodeling of DAG and TAG
Gene Ontology:
Molecular function: 1-acylglycerol-3-phosphate O-acyltransferase activity; diolein transacylation activity; long-chain fatty acyl-CoA binding; lysophosphatidic acid acyltransferase activity; lysophosphatidic acid binding; mono-olein transacylation activity; phospholipase A2 activity; triacylglycerol lipase activity; acylglycerol O-acyltransferase activity; lipoprotein lipase activity; hydrolase activity
Biological process: glycerophospholipid metabolic process; lipid droplet organization; long-chain fatty acid metabolic process; phosphatidic acid biosynthetic process; triglyceride acyl-chain remodeling; triglyceride biosynthetic process; triglyceride catabolic process; acylglycerol acyl-chain remodeling; lipid homeostasis; cellular response to 3,3',5-triiodo-L-thyronine; cellular response to insulin stimulus; lipid catabolic process; lipid metabolic process; response to sucrose; white fat cell differentiation
Cellular component: lipid droplet; membrane; endoplasmic reticulum membrane
Genetic constraint (gnomAD): Loss-of-function variants: 42 observed, 43.85 expected, observed/expected ratio (o/e) 0.96, 90% interval 0.75 to 1.24. The upper end of that interval is the gene's LOEUF score, 1.24, which puts it in group 5 of 6, group 1 being the genes least tolerant of losing a copy. Missense variants: 647 observed, 629.72 expected, observed/expected ratio (o/e) 1.03, 90% interval 0.96 to 1.1. Synonymous variants: 272 observed, 253.94 expected, observed/expected ratio (o/e) 1.07, 90% interval 0.97 to 1.18.
Homologues: Orthologues: chimpanzee PNPLA3 (98% identical), macaque PNPLA3 (93% identical), pig PNPLA3 (62% identical), dog PNPLA3 (60% identical), rat Pnpla3 (58% identical), guinea pig PNPLA3 (58% identical), mouse Pnpla3 (57% identical), tropical clawed frog pnpla3 (41% identical), zebrafish pnpla3 (39% identical). Paralogues in human: PNPLA2 (37% identical), PNPLA5 (32% identical), PNPLA1 (25% identical), PNPLA4 (17% identical).
Diseases named in the same sentence as PNPLA3 in open-access papers:
PNPLA3 is named in the same sentence as 128 diseases in open-access papers, as found by Europe PMC text mining. Sharing a sentence is not in itself a finding about the gene and the disease. The quoted sentences say what the papers report.
Hepatic steatosis (288 papers, 2009 to 2026). Steatosis is a term used to denote lipid accumulation within hepatocytes. "We aimed to investigate the relationship between serum ferritin, hepatic steatosis, metabolic risk clustering, and the PNPLA3 rs738409 gene variant in children." (PMID 41977232, 2026). "The region exhibits a distinct "African Paradox" with a lower frequency of the PNPLA3 genetic risk variant (13.7%), which contributes to lower hepatic steatosis on imaging despite pronounced insulin resistance." (PMID 41907541, 2026). "Background/Objectives: We aimed to identify eating habits associated with hepatic fat fraction (HFF) and assess effect modification by an established genetic variant for fatty liver disease, PNPLA3 rs738409, among 381 general-risk adolescents." (PMID 41978137, 2026). "Among all studied genetic variants, the patatin-like phospholipase domain containing 3 (PNPLA3) gene is the most established variant associated with an increased likelihood of liver steatosis and liver injury in children and adolescents." (PMID 41230444, 2025). "The PNPLA3 rs738409 G allele predisposes to fatty liver while modestly protecting against coronary artery disease." (PMID 40301749, 2025). "In a study examining the effects of NAFLD-associated SNPs in patients with HBV infection, only patatin-like phospholipase domain-containing protein 3 (PNPLA3) SNP was significantly associated with hepatic steatosis." (PMID 40655152, 2025). "According to GWAS studies, the PNPLA3 gene polymorphisms rs738409 and rs2896019 are associated with hepatic steatosis, inflammation, fibrosis, cirrhosis, and even hepatic cancer." (PMID 40864759, 2025). "This variant (PNPLA3 SNP rs738409) is strongly linked to hepatic steatosis, steatohepatitis, fibrosis, and hepatocellular carcinoma (HCC)." (PMID 39860434, 2025). "Among these, the PNPLA3 gene polymorphism rs738409 C>G represents the most robust determinant of hepatic steatosis susceptibility influencing lipid metabolism through the hydrolysis of triglycerides and the regulation of fat storage within the liver." (PMID 40507673, 2025). "It appears that patients with NAFLD who have patatin-like phospholipase domain-containing protein 3 (PNPLA3) are more susceptible to the positive effects of lifestyle changes on liver steatosis." (PMID 40278401, 2025). "Carrier status for the PNPLA3 rs738409 polymorphism, rs738409, which is common (gnomAD minor allele frequency 0.38 in East Asians) and associated with hepatic steatosis is also provided." (PMID 38321009, 2024). "Genetic Biomarkers: Genetic variants associated with hepatic steatosis, such as PNPLA3 and TM6SF2 polymorphisms, have been studied as predictors of disease progression." (PMID 38668326, 2024). "Even though men are more vulnerable to developing every stage of hepatic steatosis than females, studies have shown that women carrying the PNPLA3- I148M variant can be at greater risk of developing MASLD than men." (PMID 40988882, 2024). "The Human PNPLA3-I148M variant increases the accumulation of polyunsaturated fatty acids within the liver and predisposes an individual to hepatic steatosis." (PMID 40988882, 2024). "The underlying mechanism by which the common missense variant p.Ile148Met (rs738409) in PNPLA3 leads to hepatic steatosis and progressive liver injury has been a topic of discussion." (PMID 38632349, 2024). "PNPLA-3 is linked to lipid accumulation in liver tissues, particularly in the progression of hepatic steatosis." (PMID 39275255, 2024). "A common genetic variant in the PNPLA3 gene (rs738409, I148M), first identified in 2008, is widely known as the greatest genetic determinant of fatty liver disease (mean allele frequency, MAF = 0.2622)." (PMID 38247511, 2024). "For example, a polymorphic variant in the patatin-like containing domain phospholipase 3 (PNPLA3) I148M variant is the major genetic risk factor for all stages of fatty liver disease via hepatic mitochondrial dysfunction." (PMID 38256199, 2024).
Hepatic steatosis (continued). "A mutation in the gene PNPLA3 that converts Ile 148 to Met is the strongest known genetic risk factor for developing fatty liver disease." (PMID 38657050, 2024). "In contrast, rs2896019 (T > G), an intronic SNP in PNPLA3, has fewer published studies but has been associated with fatty liver diseases in Asians." (PMID 39713746, 2024). "An allele in PNPLA3-(rs738409[G] encoding L148M) was related to an elevated risk of hepatic steatosis, and the prevalence of PNPLA3 rs738409 ranged by race/ethnicity." (PMID 37447183, 2023). "The association between PNPLA3 polymorphisms, hepatic steatosis, obesity, and MetS are still debated." (PMID 36675276, 2023). "A common contributor of liver steatosis worsening is the modified patatin-like phospholipase-domain containing 3 (PNPLA3) protein caused by methionine replacement at residue 148 by isoleucine." (PMID 37892698, 2023). "PNPLA3 rs738408 is another genetic factor having strong association with hepatic steatosis, as well as the severity of NAFLD-associated fibrosis/cirrhosis." (PMID 38149094, 2023). "Our results are consistent with those in the literature who have found that PNPLA3 risk allele carrier status modified the relationship between certain dietary factors and hepatic steatosis." (PMID 38068856, 2023). "Consistently, an increased diet-related adiposity was associated with an amplified PNPLA3 genetic risk of fatty liver." (PMID 36937355, 2023). "When investigating the potential effect modification, sex modified the association between tMexS and hepatic steatosis and fibrosis, while birthplace and PNPLA3 risk allele carrier status modified the relationship between tMexS and hepatic steatosis only." (PMID 38068856, 2023). "PNPLA3 rs738409 G-allele was correlated with liver steatosis and an elevated risk of progression from simple steatosis to NASH." (PMID 37632067, 2023). "PNPLA3 I148M was mainly localized to lipid droplets (LDs), which is the basis of PNPLA3 148M/M-associated hepatic steatosis." (PMID 36825197, 2023). "Effect modifications between tMexS and hepatic steatosis and fibrosis by sex, BMI, birthplace, language spoken at home, education, income, and PNPLA3 risk allele carrier status were examined." (PMID 38068856, 2023). "Diseases associated with PNPLA3 mutations include fatty liver disease and nonalcoholic steatohepatitis (NASH)." (PMID 37983749, 2023). "PNPLA3 is strongly associated with hepatic fat content and liver enzymes and is the strongest common genetic risk factor for fatty liver disease." (PMID 37078380, 2023). "Individuals carrying the risk variant p.I148M of patatin-like phospholipase domain-containing protein 3 (PNPLA3) have a higher susceptibility to fatty liver diseases and associated complications, including HCC, a cancer closely linked to chronic inflammation." (PMID 38015590, 2023). "Studies in mice confirm a role for the variant in hepatic steatosis and demonstrate dynamic regulation of Pnpla3 gene expression in response to nutrient intake and hepatic lipid content." (PMID 36243100, 2022). "Recently, two groups independently reported that the pathogenesis of hepatic steatosis in carriers of the PNPLA3 (p.Iso148Met) variant is an ABHD5-dependent process." (PMID 36355098, 2022). "Knockdown experiments in mice have shown that the accumulation of PNPLA3 per se causes fatty liver, and depletion of the protein is a potential strategy for therapeutic intervention." (PMID 35330488, 2022). "The variant rs738409 in the PNPLA3 gene is considered to be an important genetic determinant in liver steatosis and steatohepatitis." (PMID 36079710, 2022). "Carriers of the minor PNPLA3 allele are known to be at risk of the entire spectrum of progressive liver steatosis from NAFLD to NASH, fibrosis, cirrhosis, and hepatocellular carcinoma." (PMID 36555467, 2022).
Hepatic steatosis (continued). "For example, mutations in patatin-like phospholipase domain containing protein 3 (PNPLA3) are closely related to fibrosis caused by alcoholic liver injury or fatty liver." (PMID 35990625, 2022). "The PNPLA3 risk allele was associated with increased hepatic steatosis, fibrosis, and NASH (OR = 2.22, p = 0.04)." (PMID 36555467, 2022). "The human PNPLA3 I148M variant, which has significantly reduced triglyceride hydrolase activity, is one of the strongest genetic risk factors for hepatic steatosis." (PMID 36243100, 2022). "It would be of interest to generate cell lines from individuals with the PNPLA3 polymorphism, which can predispose them to fatty liver disease." (PMID 36009822, 2022). "Pnpla3 (patatin-like phospholipase domain-containing 3) codes for a protein that has been linked to the progression of fatty liver disease, including nonalcoholic steatohepatitis, and lies downstream of SREBP-1c, an important regulator of fatty acid synthesis." (PMID 35308230, 2022). "Important progress in understanding the ATGL-independent functions of ABHD5 in hepatic lipid and energy metabolism has been made when a PNPLA3 gene variant was associated with the pathogenesis of fatty liver disease in patients." (PMID 36355098, 2022). "In keeping with a causal role of liver damage in determining a procoagulant status, the main fatty liver inherited risk variant PNPLA3 p.I148M was independently associated with the F8/PC ratio (p = 0.048)." (PMID 36313186, 2022). "We further determined that increases in the expression of FASN and PNPLA3 can cause increases in triglycerides levels, facilitate the detection of hepatic steatosis, and abolish IS." (PMID 33401717, 2021). "PNPLA3 genetic variant, rs738409, is a significant genetic risk factor for hepatic steatosis by accumulating high lipid droplets." (PMID 34635168, 2021). "Studies have shown that loss of function of PNPLA3 leads to increased hepatic steatosis and elevated serum alanine aminotransferase (ALT) and aspartate aminotransferase (AST) levels." (PMID 34040583, 2021). "Chronic overexpression of PNPLA3 in the liver under the human APOE promotor with a hepatic enhancer sufficiently caused hepatic steatosis in a transgenic mouse model." (PMID 34503201, 2021). "Patatin like phospholipase domain-containing 3 (PNPLA3) rs738409 polymorphism has been reported to be associated with hepatic steatosis, steatohepatitis and liver fibrosis in patients with NAFLD." (PMID 34876018, 2021). "We utilized a well-characterized cohort of ethnically and racially diverse patients with HIV to define the prevalence of PNPLA3 SNPs (single nucleotide polymorphism) (rs738409), and to determine the relationship to hepatic steatosis and liver fibrosis." (PMID 33800964, 2021). "The causal Pnpla3 variant, I148M, resulted in hepatic steatosis only if mice were fed a high-sucrose diet." (PMID 32859645, 2021). "Patatin-like phospholipase domain-containing protein 3 (PNPLA3) polymorphism has been related to the onset of liver steatosis mainly via the impairment of very low density lipoprotein (VLDL) secretion and increased lipogenesis." (PMID 34944730, 2021). "This study aims to systematically review and meta-analyse the association between PNPLA3 rs738409 polymorphism and non-alcoholic fatty liver." (PMID 34147109, 2021). "The rs738409 G-allele encoding the I148M variant of patatin-like phospholipase domain-containing protein 3 (PNPLA3) has been linked to hepatic steatosis and liver fibrosis in patients with CHC." (PMID 33917196, 2021). "This study aims to systematically review and meta-analyze the association between PNPLA3 rs738409 polymorphism and non-alcoholic fatty liver." (PMID 34147109, 2021). "PNPLA3 eventually causes glycerolipid hydrolasis in the liver and inhibits lipid outflow into peripheral adipose tissue, thus contributing to hepatic steatosis and related disorders." (PMID 34147109, 2021).
Hepatic steatosis (continued). "Particularly, PNPLA3 polymorphisms (I148M) are strongly associated with hepatic steatosis caused by accumulation of PNPLA3 on hepatic lipid droplets." (PMID 34557535, 2021). "TM6SF2 (rs58542926 c.499C > T) and PNPLA3 (rs738409 c.444C > G) polymorphisms were evaluated regarding their association with clinical and laboratory data, histological liver steatosis and fibrosis, and with components of the metabolic syndrome." (PMID 33622266, 2021). "The PNPLA3 variant seems not only to be a risk factor for developing fatty liver, but, even more interestingly, has been shown to be responsible for the degree of hepatic injury." (PMID 34444932, 2021). "A single nucleotide polymorphism (rs738409; C>G) in the PNPLA3 gene encoding the I148M variant is responsible for the heightened risk of the full spectrum of fatty liver disease." (PMID 33926085, 2021). "A diet rich in PUFA improved fatty liver disease in obese adolescents, and patients with the PNPLA3 rs738409 variant tended to have a better response to the dietary intervention." (PMID 34503201, 2021). "While carriers of PNPLA3 polymorphism (rs738409/I148M) are associated with hepatic steatosis and impaired lipid metabolism and hepatic steatosis was frequently seen in our HH cohort, we analyzed PNPLA3 polymorphism." (PMID 32680469, 2020). "When mice, carrying a mutation at position 148 of the Pnpla3 gene were fed a high-sucrose diet, animals displayed increased levels of triglycerides and fatty acids, resulting in increased hepatic steatosis." (PMID 32046285, 2020). "Among NAFLD-associated SNPs evaluated, only the PNPLA3 SNP was significantly associated with the presence of hepatic steatosis in a total of 224 HBV-infected patients (P = 1.0 × 10−4)." (PMID 32349377, 2020). "Allele frequency of the PNPLA3 rs738409 risk allele is lower in African Americans, thus African American obese youth possess some protection from liver steatosis." (PMID 32561908, 2020). "Patatin-like phospholipase domain 3, PNPLA3 (rs738409), was the single variant strongly associated with hepatic steatosis." (PMID 32685690, 2020). "The presence of the PNPLA3 148M variant is associated with hepatic steatosis in GWAS population studies and the lowering of PNPLA3 expression with antisense oligonucleotides has been shown to reduce hepatic fat in rodents." (PMID 33036387, 2020). "For example, people with PNPLA3 variant are usually considered to have more hepatic steatosis, inflammation, and fibrosis." (PMID 33363067, 2020). "Further studies showed the PNPLA3 variant not only increases the odds of developing fatty liver itself, but it also determines the degree of hepatic injury and the full spectrum of histopathologic consequences of MAFLD." (PMID 33363067, 2020). "Two variants of the triacylglycerol lipase gene PNPLA3 have been associated liver disease, one linked to severity of hepatic steatosis while the other affects hepatic triglyceride content by association with TM6SF2, a regulator of hepatic fat metabolism." (PMID 32280452, 2020). "In contrast, a missense genetic variant in PNPLA3 (I148M) in humans is strongly associated with fatty liver disease by reduced hydrolase activity and disruption of Pnpla2/ATGL function on the lipid droplet surface." (PMID 33013449, 2020). "The patatin‐like phospholipase domain‐containing protein 3 (PNPLA3) I148M variant predisposes to hepatic steatosis and progression to advanced liver injury with development of fibrosis, cirrhosis, and cancer." (PMID 31497741, 2019). "Genome-wide association studies have revealed that the patatin-like phospholipase domain-containing protein 3 (PNPLA3) I148M variant is associated with a higher risk of hepatic steatosis, fibrosis, and HCC." (PMID 31614590, 2019). "It is interesting to note that the well-known PNPLA3 variant associated with fatty liver disease (I148M) accumulates on lipid droplets, and similarly reorganizes the lipidome and proteome to promote liver disease progression." (PMID 31621579, 2019).